TIMP1 (TIMP metallopeptidase inhibitor 1)
Diseases named in the same sentence as TIMP1 in open-access papers (continued):
Sharing a sentence is not in itself a finding about the gene and the disease.
tumor (continued). "TIMP1 expression in tumor epithelial and stromal cells show divergent associations with T cell infiltrates in tumors and patient outcome, suggesting that TIMP1 may harbor compartment-dependent functions within the tumor microenvironment." (PMID 39789100, 2025). "Additionally, TIMP1 can influence immune cell activities, potentially shaping tumor-associated immune reactions." (PMID 39789100, 2025). "In addition, high TIMP1 expression on tumor cells has also been associated with worse prognosis, as well as with changes in immune infiltration." (PMID 39789100, 2025). "Additionally, high TIMP1 histoscore in tumor cells associated with high mGPS (p < 0.001), while high TIMP1 histoscore in stromal cells associated with high mGPS (p = 0.009) and lower stage (p = 0.047)." (PMID 39789100, 2025). "TIMP1 has been implicated in multiple aspects of tumor progression within the tumor microenvironment, although the specific immune cell populations responsible for its tumor-promoting effects remain uncleard." (PMID 41511313, 2025). "Furthermore, TIMP1 correlates with various immune cell markers, particularly those of tumor-associated macrophages, suggesting its broader role in orchestrating the immune microenvironment." (PMID 41393260, 2025). "Elevated levels of TIMP-1 could be linked to heightened tumor invasiveness and an unfavorable prognosis." (PMID 38627939, 2024). "TIMP1-deficient conditions decreased tumor growth in vitro and in vivo." (PMID 38172678, 2024). "However, it also confirmed that TIMP1 gene expression varied within tumor tissues, and higher expression was associated with shorter patient survival." (PMID 37509417, 2023). "Furthermore, network analysis links these key TF modules to open chromatin regions in genes associated with M2 polarization, tumor growth, and metastasis, including IL-10, TIMP1, and EREG." (PMID 37365178, 2023). "TIMP-1 has been associated with the tumor aggressive phenotype in various cancers." (PMID 37626157, 2023). "Furthermore, we assessed the association between TIMP1 and tumor-infiltrating cells among multiple forms of human cancer in TIMER database." (PMID 35778451, 2022). "Furthermore, TIMP1 was particularly correlated with the immune marker of macrophage M1, macrophage M2, neutrophils, tumor-associated macrophage, and Tregs." (PMID 35685428, 2022). "Therefore, the proteins encoded by POSTN and TIMP1 have the possibility of being potential tumor-associated antigens, and we further detected the level of anti-TAA autoantibodies in the subjects’ serum by ELISA experimental." (PMID 35559040, 2022). "Indeed, TIMP1 was previously demonstrated to correlate with immune markers such as M1 macrophage, M2 macrophage, tumor-associated macrophage, Tregs, and neutrophils." (PMID 36499502, 2022). "Furthermore, an association between the increased expression of TIMP-1 in tumor cells and/or stroma and the recurrence rate of eyelid BCC was identified." (PMID 34204372, 2021). "Moreover, transcript levels of genes associated with CRC susceptibility loci (e.g., Grem1 and Bmp4) and tumor development and invasion (e.g., Wnt5a, Ereg, Mmp3, Mmp13, Timp1, Saa3, Ptgs2, and Acsl4) were elevated in IL-11+ fibroblasts." (PMID 33863879, 2021). "In addition to that, TIMP-1 is also a validated target of hsa-miR-1293 and its increased expression is associated with a worse prognosis in ccRCC patients, which reinforces the tumor suppressor role of hsa-miR-1293." (PMID 32498409, 2020). "Elevated levels of TIMP-1 mRNA and TIMP-1 protein are found in different types of cancer, and several clinical studies have shown positive associations of high TIMP-1 expression with a poor prognosis or tumor progression in lung, brain, prostate, breast, colon, and other cancers." (PMID 33419373, 2020).
tumor (continued). "This paradoxical observation of NFκB P65 may be a compensatory feedback mechanism to overcome loss of IL-6 along with TIMP-1 knockdown since the NF-kB-IL-6-STAT3 cascade is an important regulator of tumor cell proliferation and survival." (PMID 31443242, 2019). "Also, TIMP-1 initiates the transformation from liver fibroblasts to carcinoma-associated fibroblasts in the tumor milieu of HCC in progression." (PMID 31886121, 2019). "Gelatinase B/MMP-9 activates pro-inflammatory cytokines TNFα and IL-1β, increases the activity of chemokines CXCL1, CXCL4, CXCL7 and CXCL8, releases TGFβ from matrix stores, is released by activated neutrophils in TIMP-1-free form and acts as a nanomolar effector of tumour associated inflammation." (PMID 24473089, 2014). "However during later stages of tumor growth, aberrant glycosylation of TIMP-1 was observed with resulting loss of TIMP-1 inhibition of collagenases, fostering more invasive tumors." (PMID 24518611, 2014). "Moreover, high levels of TIMP1 in tumor tissue are strongly associated with poor response to chemotherapy." (PMID 23522389, 2013). "The mechanism behind the observed increase in plasma TIMP-1 may be partly associated to cellular disintegration (tumor cells and/or blood cells) with subsequent release of soluble TIMP-1." (PMID 23202950, 2012). "In metastatic breast cancer patients, we reported that a high level of TIMP-1 in the primary tumor tissue is associated with decreased objective response to chemotherapy, and a report showing a similar association in the adjuvant setting was recently presented." (PMID 19744322, 2009). "This suggests that high tumor tissue levels of TIMP-1 might be associated with reduced benefit from classical adjuvant chemotherapy." (PMID 19744322, 2009). "We hypothesize that TIMP-1 high tumors are less sensitive to chemotherapy and accordingly that high tumor tissue levels are associated with shorter survival." (PMID 19744322, 2009). "A low urinary MMP9 : TIMP1 ratio was also shown to indicate an increased risk of tumour recurrence." (PMID 15083203, 2004). "TIMP-1 is another protein that has been implicated in tumor growth." (PMID 15291964, 2004). "TIMP1-related regulatory programs may contribute to macrophage-associated tumor progression." (PMID 42220487, 2026). "MMPs (e.g., MMP-2, MMP-9) are involved in extracellular matrix degradation, with their overexpression linked to tumor invasion and metastasis, while TIMPs (e.g., TIMP-1, TIMP-2), as natural inhibitors of MMPs, may exacerbate disease progression when their expression is imbalanced." (PMID 40332776, 2025). "Moreover, the scRNA-seq analysis showed that TIMP1 is mostly expressed in macrophages, which maybe regulate the biological function of tumor-associated macrophages in the microenvironment of LGG." (PMID 37264314, 2023). "Additionally, TIMP1 expression is also correlated with immune markers, especially those commonly seen in macrophages that are in M1 or M2 phase, suggesting that TIMP1 may have regulative effects on tumor-associated macrophage polarization." (PMID 35778451, 2022). "In addition, with enhanced resorption of tumour stroma, free TIMP-1 may be consumed by the various MMPs implicated in this process." (PMID 12698191, 2003). "Expression of SOX9/TIMP1/PI3K pathway components in tumor tissues was examined by immunohistochemistry and Western blotting." (PMID 41270217, 2026). "Compared with normal controls, the relative mRNA expression levels of NOX4, SCD, and TIMP1 were significantly higher in tumor tissues, while those of AQP8 and NR5A2 were significantly lower." (PMID 41438584, 2026). "This persistent overexpression pattern suggests TIMP1 plays a more substantial role in epithelial cell differentiation within tumor tissues." (PMID 41187171, 2025). "Among these, TIMP1 emerged as particularly noteworthy, exhibiting the highest overall expression in tumor samples and showing strong positive correlations with multiple pro-tumorigenic functional states." (PMID 41187171, 2025).
tumor (continued). "Given that the hepatic immune microenvironment undergoes reprogramming prior to the arrival of tumor cells to establish a pre-metastatic niche, we further investigated the role of TIMP1 in this process." (PMID 41511313, 2025). "IR contributes to tumor progression by generating truncated oncogenic proteins, suppressing tumor suppressor genes like TIMP1 and DMD, and enabling cancer cells to adapt to stressors like hypoxia." (PMID 40870034, 2025). "Our results highlight the role of TIMP1 in regulating ferroptosis pathways, which are crucial for tumor progression, and exposes a potential therapeutic target for PCa management." (PMID 40185230, 2025). "Cells harboring either sh-control or sh-TIMP1 lentiviral vectors underwent subcutaneous transplantation into nude mice, with subsequent monitoring of tumor progression for 27 days." (PMID 40777024, 2025). "T cell densities in tumor tissue positively correlated with tumor stromal TIMP1 expression and negatively with tumor epithelial TIMP1 expression." (PMID 39789100, 2025). "We further analyzed the expression patterns of the 7 model genes in tumor tissues, revealing that TIMP1 exhibited the highest expression level among them." (PMID 41187171, 2025). "This interplay underscores the need to stratify TIMP1-targeted therapies based on tumor stage, metabolic state, and TIMP1 expression levels." (PMID 40185230, 2025). "The expression levels of the genes CD36, CXCL14, DAB2, MARCKS, ENPEP, and TIMP1 in normal, tumor, and metastatic tissues were analyzed using various statistical methods." (PMID 40565366, 2025). "CRC cells secreted TIMP1 into the tumor microenvironment, where it induced M2-like macrophage polarization and increased the expression of immunosuppressive mediators such as CSF1 and IRF4." (PMID 41511313, 2025). "Retinoic Acid can bind closely with TIMP1, downregulate TIMP1 expression, inhibit tumor growth, and induce tumor cell differentiation." (PMID 40244296, 2025). "In this study, we analyzed TIMP1 expression in tumor epithelial and stromal cells, as well as TIMP1 serum levels, in a cohort of 776 CRC patients (606 with preoperative serum TIMP1 data and 757 with tissue TIMP1 data)." (PMID 39789100, 2025). "Elevated TIMP1 expression has been reported in multiple cancers, including lung, breast, and PCas, often correlating with aggressive tumor behavior and poor prognosis." (PMID 40185230, 2025). "ROC analyses showed that TIMP1 histoscore in stromal cells had higher AUC values than TIMP1 histoscore in tumor cells." (PMID 39789100, 2025). "Among systemic inflammatory markers and blood cell counts, serum albumin levels inversely correlated with TIMP1 histoscores in both tumor and stromal cells (p < 0.001 for both)." (PMID 39789100, 2025). "Secondly, double glycosylated TIMP-1 was the most efficient TIMP-1 variant to interact with CD63, promoting tumor cell proliferation and survival." (PMID 40345589, 2025). "Collectively, these results demonstrate that TIMP1 overexpression significantly reduces tumorigenicity and metastatic potential in PCa, underscoring its role as a key regulator of tumor progression." (PMID 40185230, 2025). "NDs with a higher sp3/sp2 carbon ratio effectively reduce the proangiogenic activity of tumor cells by downregulating key cytokines such as IL-6, IL-8, TIMP-1, TIMP-2, ANG, and ANGPTs." (PMID 40804455, 2025). "TIMP1 as a matrix metalloproteinase inhibitor, TIMP1 regulates matrix remodeling in the tumor microenvironment and promotes tumor metastasis." (PMID 40190762, 2025). "Strikingly, only three genes - ITGB4, LDHA, and TIMP1 – showed significantly elevated expression in tumor epithelial cells compared to their normal counterparts (P < 0.01)." (PMID 41187171, 2025). "The peripheral levels of TRIM44, CTSZ, CD164, and TIMP1 can stimulate granulocyte production in mouse bone marrow, and high levels of TIMP1 are positively correlated with increased immune infiltration levels of tumor-infiltrating lymphocytes." (PMID 40524208, 2025).
tumor (continued). "Strikingly, only three genes—ITGB4, LDHA, and TIMP1—demonstrated significantly higher expression in tumor epithelial cells compared to their normal counterparts." (PMID 41187171, 2025). "TIMP1 histoscore in tumor and stromal cells showed distinct correlations with T cell densities in a consistent pattern across the whole tumor, CT, and IM levels." (PMID 39789100, 2025). "By secreting specific cytokines and chemokines such as CCL2, ApoE, and TIMP1, it promotes the invasion and metastasis of tumor cells." (PMID 40495209, 2025). "This demonstrates that TIMP-1 glycosylation is not necessary for the execution but rather for the modulation of the antiproteolytic activity of TIMP-1, while glycosylation was necessary to execute the tumor-promoting cytokine-like effects of TIMP-1 via CD63." (PMID 40345589, 2025). "TIMP1 can trigger monocyte and neutrophil activation and cytokine production, and hence TIMP1 is a potential tumor-derived factor driving systemic inflammation in CRC." (PMID 39789100, 2025). "Immunohistochemical (IHC) analysis demonstrated significantly higher TIMP1 expression in tumor regions compared to adjacent normal tissues." (PMID 41187171, 2025). "We separately measured TIMP1 expression in tumor epithelial cells and stromal cells using the histoscore method, with tumor epithelial and stromal histoscores showing positive correlation (r = 0.76, p < 0.001)." (PMID 39789100, 2025). "Pseudotime trajectory analysis of epithelial cells revealed that TIMP1 maintained consistently elevated expression throughout the entire differentiation continuum in tumor epithelial cells compared to normal cells." (PMID 41187171, 2025). "Tissue inhibitor of metalloproteinases-1 (TIMP1) is a multifunctional matrix metalloproteinase inhibitor that promotes tumor cell survival and angiogenesis by binding to the STAT3 pathway." (PMID 41189944, 2025). "To explore the potential role of TIMP1 in tumor-host interactions, we analyzed the correlations of TIMP1 expression in tumor tissue with T cell densities, tumor necrosis percentage, systemic inflammation markers, and blood cell counts." (PMID 39789100, 2025). "The xenograft tumor tissues constructed in the previous stage were sectioned, and then immunohistochemical analysis was performed to evaluate the expression of TIMP1 and PD-L1." (PMID 40290432, 2025). "Our previous experiments demonstrated that glycosylation macroheterogeneity of TIMP-1 modulates its multifunctionality, where N30-glycosylation was important for the tumor-promoting cytokine-like activity." (PMID 40345589, 2025). "First, TIMP1 concentrations and immune cell densities were defined using TMAs, which only represent small tumor areas." (PMID 39789100, 2025). "The glycosylation-dependent modulation of the multifunctionality of tumor-secreted TIMP-1 thus provides a molecular basis for its long-debated cancer-promoting role." (PMID 40345589, 2025). "For instance, tissue inhibitor of metalloproteinases-1 (TIMP-1) and matrix metalloproteinases (MMPs) have shown encouraging diagnostic accuracy in population studies, reflecting tumor invasion and tissue remodelling processes." (PMID 41294737, 2025). "TIMP1 expression in tumor epithelial and stromal cells was analyzed with immunohistochemistry (IHC) combined with supervised machine learning based image analysis, facilitating consistent analysis across a large number of cases." (PMID 39789100, 2025). "Further analysis of ferroptosis pathway proteins, including TF, GCLC, and GCLM, demonstrated differential involvement in TIMP1-overexpressing and TIMP1-knockout cells and tumor tissues." (PMID 40185230, 2025). "In immunohistochemical analysis, anti-TIMP1 antibody labeled tumor epithelial cells with varying intensities, necrosis strongly, and stroma (including immune cells) more diffusely with generally weaker intensity." (PMID 39789100, 2025).
tumor (continued). "This contradicts the known role of TIMP1 as a natural inhibitor that can modulate the invasive and metastatic capacity of tumor cells." (PMID 40427104, 2025). "The M17 gene module comprises core genes including TIMP1, TFF2, ITM2A, SPINK1, and TSPAN8, intimately associated with tumor stemness maintenance and invasion-metastasis capacity." (PMID 41450464, 2025). "Serum TIMP1 levels also showed a weak positive correlation with tumor necrosis percentage (beta = 0.091, p = 0.034)." (PMID 39789100, 2025). "Necrotic regions within tumors showed intensive TIMP1 staining, and serum TIMP1 levels positively correlated with tumor necrosis percentage." (PMID 39789100, 2025). "TIMP1, a tissue inhibitor of matrix metalloproteinases (TIMMPs), is recognized for its potential to hinder tumor process." (PMID 40362553, 2025). "Tumor necrosis percentage negatively correlated with TIMP1 histoscore in tumor cells (beta=-0.14, p < 0.001)." (PMID 39789100, 2025). "Subsequent investigations revealed that IL-12A overexpression stimulated the expression of angiogenesis-associated proteins TIMP1, IGFBP1, and PAI1 in tumor cells." (PMID 39974277, 2025). "High TIMP1 serum levels associated with MMR deficient status, high ASA classification, older age, elevated mGPS (all p < 0.001), proximal tumor location (p = 0.032), and BRAF mutation (p = 0.006)." (PMID 39789100, 2025). "The observed expansion of Treg populations in tumor tissues, coupled with the identified epithelial-Treg signaling networks, prompted systematic investigation of TIMP1’s immunomodulatory role." (PMID 41187171, 2025). "Secondly, the M2-polarized macrophages are mainly composed of M2-like tumor-associated macrophages (TAMs) with tumor-promoting characteristics (CD163, FTH1, FTL, TIMP1), and there is a polarization from M1 to M2." (PMID 40948800, 2025). "In parallel, tumor-derived TIMP1 stimulates Schwann-cell proliferation and secretion of CCL7, which in turn enhances tumor cell migration and PNI." (PMID 41394398, 2025). "In an orthotopic PDAC model, TRPV4-KO mice exhibited a significant reduction in tumor size, circulating inflammatory cytokines, tissue inhibitor of metalloproteinases-1 (TIMP1), and premetastatic niche markers, serum amyloid A (SAA) proteins." (PMID 41100488, 2025). "All tumour cells expressed TIMP1 in the cytosol to varying levels in the primary tumours and the paired metastatic mesenteric masses." (PMID 40998421, 2025). "While initially considered a tumor suppressor due to its anti-proteolytic activity, TIMP1 is now recognized to promote tumorigenesis by regulating cell proliferation, apoptosis resistance, and metastasis through MMP-independent pathways." (PMID 41511313, 2025). "Survival analysis demonstrated that TIMP1 knockdown significantly prolonged the overall survival of tumor-bearing mice compared to vehicle-treated controls, indicating that TIMP1 plays a critical role in promoting CRLM and contributes to poor prognosis." (PMID 41511313, 2025). "Like TIMP1 and ICAM1, CTSD is typically overexpressed in PDAC and has been implicated in cancer cell proliferation, migration, and tumor invasion." (PMID 40507347, 2025). "For instance, TIMP1 has been shown to be packaged into EVs and promote tumor invasiveness via extracellular matrix remodeling." (PMID 40565366, 2025). "Among these, TIMP1 emerged as particularly noteworthy, exhibiting the highest overall expression in tumor samples and strong positive correlations with multiple pro-tumorigenic functional states." (PMID 41187171, 2025). "This supports clinical trials combining primary tumor resection with TIMP-1-targeting or neutrophil-modulating therapies in patients at high risk for liver metastasis." (PMID 41463352, 2025). "As the result shown, MPS with high expression of TIMP1 were distributed more within the tumor, while MPS with high expression of TIMP2 were distributed more in stroma." (PMID 38408082, 2024).